SHANK3 (SH3 and multiple ankyrin repeat domains 3)
Diseases named in the same sentence as SHANK3 in open-access papers (continued):
Sharing a sentence is not in itself a finding about the gene and the disease.
autism spectrum disorder (continued). "The PSD genes are extremely sequence conserved, and comprise scaffolding proteins, such as SHANK3 and NRXN1 genes, which are recurrently described with mutations in autism spectrum disorder and schizophrenia." (PMID 29531218, 2018). "Multiple point mutations, deletions, and truncations occur in SHANK1–3 in people with autism spectrum disorders (ASD), with SHANK3 mutations mainly found in ASD individuals with moderate to severe intellectual disability." (PMID 30405356, 2018). "Genetic variations of SHANK3, together with those for SHANK2, are strongly associated with diverse brain dysfunctions, including autism spectrum disorders (ASDs) Phelan-McDermid syndrome, schizophrenia, and intellectual disability." (PMID 25852484, 2015). "In view of the role of SHANK3 in neurodevelopmental, neurobehavioral and autism spectrum disorders, future work to decipher the functional role of this 75aa N-terminal domain and its interaction with MCC is now warranted." (PMID 25997006, 2015). "BACKGROUND: Autism spectrum disorder (ASD) is a neurodevelopmental disorder with a strong genetic component, and over a thousand associated genes have been identified, including CNTNAP2 and SHANK3." (PMID 42010670, 2026). "Finally, a study assessed two different types of mice (Shank2 and Shank3) in an autism spectrum disorder model, in which mice had to coordinate their running through a maze to receive a reward." (PMID 39509367, 2024). "However, there are also some mice models of neuropsychiatric disorders that exhibit increased PPI, like schizophrenia-related Neurolign2 R215H knockin mice and autism spectrum disorder (ASD)-related Shank3 knockout mice (Shank3tm2Gfng)." (PMID 37480133, 2023). "In a mouse model of autism spectrum disorders, a truncated mutant form of Shank3 displayed altered plasticity, anxiety-like, motor, social, communications and stereotyped behaviors, which were attributable to reduced synaptic plasticity in the hippocampal–medial prefrontal cortex pathway." (PMID 35328058, 2022). "Similarly, activity of glutamatergic pyramidal neurons of the anterior cingulate cortex is required for normal social behavior, and these neurons are primarily affected in the Shank3 knockout model of autism spectrum disorder." (PMID 35247972, 2022). "In addition, point mutations of the SHANK3 gene account for ~1% of the idiopathic forms of autism spectrum disorder, and SHANK3 haploinsufficiency is responsible for the major neurological features of PMS." (PMID 35250656, 2022). "Synapse-associated gene mutations of SH3 and multiple ankyrin repeat domains protein 3 (SHANK3) may lead to autism spectrum disorder (ASD)." (PMID 35401120, 2022). "Several genes were validated in APA sperm that were associated with autism spectrum disorder (CACNA1H, CNTNAP2, GRIN1, SHANK2, SHANK3, ZNF804A), schizophrenia (TCF3, ZNF804A), and bipolar disorder (COMT, DRD4, GRIN1, MBP, PRKCZ, SHANK2, TRPM2, ZNF804A), and in APA blastocysts (CACNA1H)." (PMID 32610362, 2020). "Phelan-McDermid syndrome (PMS) is a rare genetic disorder characterized by global developmental delay, intellectual disability (ID), autism spectrum disorder (ASD), and mild dysmorphisms associated with several comorbidities caused by SHANK3 loss-of-function mutations." (PMID 31319798, 2019). "Mutations within the Shank3 gene, which encodes a key postsynaptic density (PSD) protein at glutamatergic synapses, contribute to the genetic etiology of defined autism spectrum disorders (ASDs), including Phelan-McDermid syndrome (PMS) and intellectual disabilities (ID)." (PMID 30971895, 2019). "The 22q13 region contains the SHANK3 gene: haploinsufficiency of SHANK3 is proposed to cause the major features of PMS, and mutations in the SHANK1, SHANK2 and SHANK3 genes are associated with autism spectrum disorder." (PMID 29126394, 2017).
autism spectrum disorder (continued). "Deletions and mutations involving the SHANK3 gene lead to a nonspecific clinical presentation with moderate to profound intellectual disability, severely delayed or absent speech, and autism spectrum disorders (ASD)." (PMID 26489495, 2015). "Although mutations in all three SHANK genes are associated with autism spectrum disorder (ASD), SHANK3 appears to be the major ASD gene with a prevalence of approximately 0.5% for SHANK3 mutations in ASD, with higher rates in individuals with ASD and intellectual disability (ID)." (PMID 26045941, 2015). "Given that SHANK3 is mutated in its SPN domain in a spectrum of neuropsychiatric disorders including autism spectrum disorder, it might be of interest to further explore the Rap1–talin–integrin axis in neurons expressing WT and mutant SHANK3." (PMID 39853211, 2025). "However, while SHANK3 has been the subject of extensive research in the field of autism spectrum disorder, its role in age-related cognitive disorders, such as AD, remains unclear." (PMID 37253603, 2023). "We further showed that gintonin successfully induced dendritic growth in striatal neurons, in which dendritic complexity was reduced by Slitrk5 and Shank3 knockdown, and could alleviate certain phenotypes related to obsessive–compulsive disorder and autism spectrum disorder." (PMID 36385759, 2022). "Therefore, just as neurotypical individuals and autism spectrum disorder individuals exhibit different behavioral strategies when performing goal-directed tasks, wild-type and Shank3 KO mice developed cricket hunting behaviors with distinct features." (PMID 36446569, 2022). "SHANK3 (SH3 and multiple ankyrin repeat domains 3, also known as proline-rich synapse-associated protein 2 (ProSAP2)) is a known scaffolding protein of the postsynaptic density (PSD) of glutamatergic excitatory synapses that has been associated with autism spectrum disorders (ASD)." (PMID 31052177, 2019). "Heterozygous deletion or mutation of SHANK3 is thought to be the cause of core neurodevelopmental and neurobehavioral deficits in the 22q13 deletion syndrome, Phelan-McDermid syndrome, an autism spectrum disorder with developmental delay, absent or delayed speech and mild facial dysmorphism." (PMID 25997006, 2015). "Two highly penetrant autism spectrum disorder genes, SCN2A and SHANK3, are represented among the top 20 genes with the highest number of DNMs." (PMID 38395944, 2024). "Loss of one functional copy of SHANK3 accounts for about 0.5% of the cases of autism spectrum disorder (ASD) and/or developmental delay, and there is likely a wider role for SHANK3 and glutamate signaling abnormalities in ASD and related neurodevelopmental disorders." (PMID 23621888, 2013).
Phelan-McDermid syndrome (135 papers, 2008 to 2026). A rare genetic neurodevelopmental disorder characterized by neonatal hypotonia, global developmental delay, normal to accelerated growth, absent to severely delayed speech, and minor dysmorphic features. "According to OMIM, Phelan-McDermid Syndrome (PMS) can be caused by a heterozygous contiguous gene deletion at chromosome 22q13 or by mutation in the SHANK3 gene (606230), which is located within the minimum critical region." (PMID 41178943, 2025). "Phelan-McDermid syndrome (PMS) is a genetic disorder caused by the loss of the terminal region of chromosome 22 or by pathogenic or likely-pathogenic variants in SHANK3 gene." (PMID 40104333, 2025). "Phelan-McDermid syndrome is a rare condition characterized by deletion or mutation within the SHANK3 gene in chromosome region 22q13.33." (PMID 40400398, 2025). "Phelan-McDermid syndrome (PMS) is a rare neurodevelopmental disorder caused by a deletion or variant of SHANK3." (PMID 41282476, 2025). "Mutations in SHANK3 are related to Phelan-McDermid syndrome, resulting in reduced postsynaptic proteins." (PMID 40519825, 2025). "SHANK3 is the main causative gene of Phelan-McDermid syndrome (PMS), and its variants are highly associated with neurodevelopmental, intellectual, psychotic, and mood disorders." (PMID 41282476, 2025). "Phelan-McDermid syndrome (PMS) is a neurodevelopmental disorder caused by SHANK3 haploinsufficiency with clinical manifestations that can be devastating and profoundly affect quality of life." (PMID 38532502, 2024). "Phelan-McDermid syndrome (PMS) is a genetic disorder caused by haploinsufficiency of SHANK3, either by 22q13 deletion or pathogenic sequence variant." (PMID 38730350, 2024). "Sleep disturbances are a significant translational phenotype in synaptopathies, such as Phelan McDermid Syndrome (mutation in or loss of Shank3) and SRID." (PMID 39358332, 2024). "Phelan-McDermid syndrome (PMS) is a genetic neurodevelopmental disorder caused by SHANK3 haploinsufficiency and is associated with an increased risk for seizures." (PMID 38730350, 2024). "SHANK3 Gene (NM_001372044.2): A splice site variant (c.13zc05-3_1,305-2delTT; p.Gln29-_Gly305del) associated with Phelan-McDermid syndrome (OMIM 606232)." (PMID 39281811, 2024). "Phelan-McDermid syndrome is caused by deletion or changing in chromosomal structure in 22q13 region or mutation in SHANK3 gene." (PMID 38451970, 2024). "In family 7, four affected individuals were found to have a splice acceptor site deletion variant (c.1305-3_1,305-2delTT; p.Gln29_Gly305del) in the SHANK3 gene (NM_001372044.2), which is associated with Phelan-McDermid syndrome (OMIM 606232)." (PMID 39281811, 2024). "Mutations of SHANK3 cause Phelan-McDermid syndrome, which is characterized by a variable phenotype of neurodevelopmental abnormalities, syndromic facial features, and cardiac abnormalities including BAV." (PMID 38370698, 2024). "Mutations in the SHANK3 (SH3 and multiple ankyrin repeat domains protein 3) gene cause ASD and Phelan-McDermid syndrome, and mouse models have provided insights into SHANK3 function." (PMID 38025664, 2023). "Among the genes shown to be linked to ASD is SHANK3, whose mutation or deletion also causes Phelan-McDermid syndrome, a condition that often presents with similar symptoms to ASD41,42." (PMID 36991001, 2023). "Phelan-McDermid Syndrome (PMD) is caused by disruption of SHANK3, usually due to deletion of chromosome 22q13.3 or sometimes de novo loss-of-function single nucleotide variants (SNVs) in SHANK3." (PMID 35203901, 2022). "Case 18 (SHANK3: c.3637dupG, p.1213fsX68), who was diagnosed with Phelan-McDermid syndrome, which is usually caused by SHANK3 deletions, developed the sudden onset of severe OCD following bacterial infections." (PMID 35773312, 2022). "Phelan-McDermid syndrome (PMS) is a neurodevelopmental disorder caused by chromosomal rearrangements affecting the 22q13.3 region or by SHANK3 pathogenic variants." (PMID 35741804, 2022).
Phelan-McDermid syndrome (continued). "Phelan-McDermid syndrome (PMS) is a rare neurodevelopmental disorder caused by haploinsufficiency of SHANK3 either by pathogenic sequence variant or by deletion." (PMID 35592263, 2022). "Heterozygous SHANK3 loss or SHANK3 mutations in humans are thought to be the major cause for the neuronal developmental disorder frequently referred to as Phelan-McDermid syndrome (PMS)." (PMID 36699652, 2022). "Most importantly, single-gene disorders characterized by ASD–epilepsy comorbidity (such as FMR1-, TSC1/2-, and SHANK3-mediated Phelan-McDermid syndromes) are caused by mutations in genes that regulate glutamate receptor-mediated signaling mechanisms." (PMID 36142719, 2022). "Phelan-McDermid syndrome (PMS) is a genetic disorder caused by a mutation or deletion of the SHANK3 gene (chromosome 22q13.3), characterized by different sensory processing anomalies." (PMID 35840778, 2022). "Phelan-McDermid syndrome (PHMDS) is a rare genetic disorder mostly caused by haploinsufficincy of SHANK3 gene, and characterized by neonatal hypotonia, developmental delay, minor dysmorphic features, seizures and behavior problems." (PMID 36528601, 2022). "Mutations in SHANK3 are also linked to another neurodevelopmental disorder, the Phelan-McDermid syndrome." (PMID 34385907, 2021). "Phelan McDermid syndrome (PMcD) is a neurogenetic disease associated with haploinsufficiency of the SHANK3 gene due to a spectrum of anomalies in the terminal region of the long arm of chromosome 22." (PMID 33669083, 2021). "Mutations in SHANK3 cause Phelan-McDermid syndrome, a developmental disorder with variable features including neonatal hypotonia, global developmental delay, absent to severely delayed speech, autistic behaviour, and minor dysmorphic features." (PMID 34356170, 2021). "Phelan-McDermid Syndrome (PMS) is a rare condition caused by deletion or mutation of the SHANK3 gene." (PMID 33910615, 2021). "SHANK3 gene mutations are strongly linked to ASD, and SHANK3 haploinsufficiency is believed to be the major contributing factor to the 22q13.3 deletion syndrome, also known as Phelan-McDermid syndrome (PMS)." (PMID 32393347, 2020). "For example, missense variants in SHANK3, the gene mutated in Phelan-McDermid syndrome (OMIM #606232), cause less severe phenotype than exonic SHANK3 deletion." (PMID 32942984, 2020). "Our work focuses on a monogenic form of ASD, Phelan-McDermid syndrome, that is caused by mutations that disrupt one copy of the SHANK3 gene resulting in SHANK3 haploinsufficiency." (PMID 30733854, 2019). "For example, mutations in SHANK3/PROSAP2 that are found in Phelan-McDermid syndrome are associated with ASD." (PMID 31744938, 2019). "The most prominent example of a SHANK3 deficiency is the 22q13.3 deletion syndrome, also known as Phelan-McDermid syndrome, however, intragenic mutations have also been found in autistic cohorts." (PMID 30853900, 2019). "Terminal 22q deletion contains 38 RefSeq genes (having 27 OMIM genes and a critical SHANK3 gene) associated with 22q13.3 microdeletion syndrome (Phelan-McDermid syndrome, PMS, OMIM: 606230)." (PMID 29467824, 2018). "Zinc deficiency has been observed in humans affected not only by ASD, but also in Phelan-McDermid syndrome in which heterozygous loss of SHANK3 occurs." (PMID 30405356, 2018). "The loss of one copy of SHANK3 (SH3 and multiple ankyrin repeat domains 3) in humans highly contributes to Phelan McDermid syndrome (PMDS)." (PMID 29875651, 2018). "Microdeletions and point mutation involving SHANK3 region have been reported as cause of a spectrum of neuropsychiatric disorders including “22q13 deletion syndrome” (also known as Phelan-Mcdermid syndrome) and ASD." (PMID 28174603, 2017). "Mutations in the synaptic gene SHANK3 lead to a neurodevelopmental disorder known as Phelan-McDermid syndrome (PMS)." (PMID 28139198, 2017).
Phelan-McDermid syndrome (continued). "The deletion region of two children is partially overlap of 22q13 deletion syndrome (Phelan-Mcdermid syndrome), and it contained its major causative gene SHANK3." (PMID 27741506, 2016). "The loss of one functional copy of SHANK3 results in Phelan-McDermid syndrome (PMS), characterized by global developmental delay, moderate to severe intellectual disability (ID), delayed or absent speech, hypotonia, and ASD or ASD features." (PMID 26909118, 2016). "Although mutations can be causal in Phelan-McDermid Syndrome, SHANK3 mutations have also been identified in several cases of idiopathic ASD." (PMID 26388713, 2015). "Recently, point mutations or micro-deletions of the SHANK3 gene have been identified, accompanied by a phenotype different from the initial clinically description in Phelan McDermid syndrome." (PMID 25947967, 2015). "SH3 and multiple ankyrin repeats 3 (Shank3)/proline rich synapse associated protein 2 (ProSap2) has been implicated to be the critical, pathologic gene responsible for Phelan-McDermid Syndrome in patients with 22q13 deletions/mutations." (PMID 26388713, 2015). "SHANK3 is the critical gene in this syndrome, and its loss is sufficient to cause Phelan-McDermid syndrome (PMS; OMIM ID 606232)." (PMID 25784960, 2014). "Loss of one functional copy of SHANK3 results in 22q13 deletion syndrome or Phelan-McDermid syndrome (PMS) and causes a monogenic form of ASD and/or ID with a frequency of 0.5% to 2% of cases." (PMID 25784960, 2014). "Altogether, in addition to the large deletions observed in Phelan-McDermid syndrome, mutations of SHANK3 account for more than 1 out of 50 cases diagnosed with the combination of ASD and ID." (PMID 25188300, 2014). "22q13.3 deletions and mutations that lead to a loss of a functional copy of SHANK3 cause Phelan-McDermid syndrome, characterized by moderate to profound intellectual disability, severely delayed or absent speech, hypotonia, and ASD or ASD traits." (PMID 23758743, 2013). "The disruption of the SHANK3/ProSAP2 gene by an apparently balanced rearrangement and the alteration of SHANK3 by a frameshift mutation have also been described as mechanisms leading to the language deficits and autistic features of Phelan-McDermid syndrome." (PMID 18505557, 2008). "• Frameshift mutation of SHANK3 has been associated with the neurological deficits in Phelan-McDermid syndrome." (PMID 18505557, 2008). "In this study, we asked whether mutation of the ASD-linked gene Shank3, linked to Phelan-McDermid Syndrome (PMS) in humans, leads to alterations in ENS and GI tract structure and function that may manifest as GI comorbidities." (PMID 40313537, 2025). "As ASD patients, including patients with Phelan-McDermid syndrome, typically carries heterozygous SHANK3 mutations, Shank3 heterozygous mutant animals may better mimic the pathophysiology and behavioral abnormalities of ASD patients." (PMID 38297387, 2024). "In particular, zebrafish larvae engineered by CRISPR-Cas9 to lack the C terminus of SHANK3 (i.e. homozygous or heterozygous shank3abΔC loss-of-function mutant models of Phelan-McDermid syndrome) display increased intestinal transit time due to reduced frequency of peristaltic muscular contractions." (PMID 39363263, 2024). "In addition, Pten, Shank3, Adnp, and Nrxn1 are associated with Cowden syndrome, Phelan-McDermid syndrome, Helsmoortel-Van der Aa syndrome, and Pitt-Hopkins-like syndrome 2, respectively." (PMID 39431203, 2024). "SHANK3 haploinsuffiency on account of the heterozygous loss of the distal arm of chromosome 22 or to mutations within the SHANK3 gene leads to a syndromic form of a neurodevelopmental autism spectrum disorder (ASD) named 22q13.3 deletion or Phelan-McDermid Syndrome (PMDS)." (PMID 36355061, 2023). "SHANK3 is located on chromosome 22q13.3, whose mutation leads to a haploinsufficiency of the SHANK3 protein and causes a rare genetic developmental disorder, called Phelan-McDermid syndrome." (PMID 37745298, 2023).